GBP1P1 (guanylate binding protein 1 pseudogene 1)
Synonyms: LIMIT
Gene: Transcribed unprocessed pseudogene on chromosome 1 (89,410,319 to 89,426,243, forward strand). Ensembl gene ENSG00000225492.
Diseases named in the same sentence as GBP1P1 in open-access papers:
GBP1P1 is named in the same sentence as 14 diseases in open-access papers, as found by Europe PMC text mining. Sharing a sentence is not in itself a finding about the gene and the disease. The quoted sentences say what the papers report.
breast carcinoma (3 papers, 2019 to 2024). "Upregulation of GBP1P1 has been reported in cervical carcinoma, breast cancer, and nasopharyngeal carcinoma." (PMID 38072995, 2023). "The GBP1-involved PGG network also contained the pseudogene GBP1P1, which may have a ceRNA regulatory role in breast cancer and in some neurodegenerative diseases." (PMID 31029062, 2019). "The pseudogene GBP1P1 (guanylate binding protein 1 pseudogene 1) was found to enhance GBP1 gene expression through the modulation of miR-30d-5p, thereby contributing to the viability, migration and clonogenicity of breast cancer cells." (PMID 38473871, 2024).
hepatocellular carcinoma (1 paper, 2024). A malignant tumor that arises from hepatocytes. "To date, GBP1P1 was found to be as significantly correlated with overall survival (OS) only in hepatocellular carcinoma (HCC) and OC patients." (PMID 39494284, 2024).
HIV-1 infection (1 paper, 2020). The type species of lentivirus and the etiologic agent of acquired immunodeficiency syndrome (AIDS). "In this study we found that GBP1P1 is induced in macrophages by every IFN-type (up to ~350 fold) and by HIV-1 infection (~3 fold)." (PMID 33086748, 2020).
ovarian carcinoma (1 paper, 2024). A malignant neoplasm originating from the surface ovarian epithelium. "To evaluate the specific role of GBP1P1 in ovarian cancer, we examined the effects of GBP1P1 knockdown on the proliferation, apoptosis, migration, and invasion of W038 cells in vitro." (PMID 39494284, 2024). "We established the ovarian cancer cell line W038 for this study and identified the performances of GBP1P1 knockdown on a series of activities including cellular proliferation, apoptosis, migration, and invasion of W038 cells in vitro." (PMID 39494284, 2024).
tularemia (1 paper, 2019). Tularemia is an infection caused by the bacterium Francisella tularensis. "Tularemia vaccine induced higher guanylate binding protein (GBP) responses at Day 2, with upregulation of genes encoding for GBP1P1, GBP5, GBP1, and GBP4 compared to the other vaccines at Day 3 (blue bracket)." (PMID 31878161, 2019).
viral infections (1 paper, 2024). "As a novel antiviral host factor, GBP1P1 may also be more broadly implicated in other viral infections." (PMID 38940585, 2024).
infection (2 papers, 2023 to 2024). The state of being infected such as from the introduction of a foreign agent such as serum, vaccine, antigenic substance or organism. "Since IAV induced the expression of GBP1P1 immediately within a few hours after infection, we speculated that GBP1P1 expression might be induced by antiviral innate immunity." (PMID 38940585, 2024). "GBP1P1 represents a pseudogene of guanylate-binding protein 1 (GBP1), which is responsible for autophagosome formation during intracellular pathogen infection." (PMID 37402153, 2023). "In a time course analysis, compared to cells transfected with negative control (NC) siRNA, A549 cells transfected with si-GBP1P1 were able to promote IAV M1 protein production much more significantly at late times (24 and 36 h) than at early times (12 h) post-infection." (PMID 38940585, 2024).
tumor (2 papers, 2023 to 2024). "Therefore, we believed that GBP1P1 was associated with the prognosis of OC, which was determined by the combined influence of complex tumor microenvironment." (PMID 39494284, 2024). "As expected, the expression of GBP1 and its pseudogene GBP1P1 were significantly higher in tumor samples." (PMID 38072995, 2023). "In the third step, the GBP1/hsa-miR-30d-5p/GBP1P1 axis expression level was assessed in 40 tumor/normal BC patients and MCF-7 cell lines." (PMID 38072995, 2023). "The expression of GBP1 and GBP1P1 was significantly higher in the tumor compared to the normal tissue." (PMID 38072995, 2023). "The expression levels of GBP1 and its pseudogene, GBP1P1, were significantly upregulated in tumor samples." (PMID 38072995, 2023). "When the relative expression of the GBP1/hsa-miR-30d-5p/GBP1P1 axis were compared to patient’s pathological data, the expression of these genes was significantly correlated to lymph nodes metastasis, cancer stage and tumor grade." (PMID 38072995, 2023). "The expression of GBP1 and GBP1P1 in tumor tissue was 3.4-fold and 5.7-fold higher, respectively." (PMID 38072995, 2023).
cancer (1 paper, 2023). A tumor composed of atypical neoplastic, often pleomorphic cells that invade other tissues. "However, the underlying mechanism of GBP1/hsa-miR-30d-5p/GBP1P1 axis function in cancer needs further investigations." (PMID 38072995, 2023).
GBP1P1 also shares sentences with these, for which no sentence is quoted: cervical carcinoma (2 papers); choriocarcinoma (1); endometriosis (1); gastric cancer (1); neurodegenerative disease (1).